BAP1 (BRCA1 associated deubiquitinase 1)
Diseases named in the same sentence as BAP1 in open-access papers (continued):
Sharing a sentence is not in itself a finding about the gene and the disease.
breast carcinoma (79 papers, 2010 to 2025). "Recent studies have revealed that BAP1 exhibits oncogenic functions in malignancies such as breast cancer and myeloid leukemia, which are associated with its biological activities." (PMID 40918144, 2025). "Mutations of BAP1 have been included in the HR-deficiency-associated pathways in breast cancer, particularly in the TNBC subtype, characterized by a relative high mutation frequency." (PMID 37813891, 2023). "Despite initial identification as a tumor suppressor in lung and breast cancer, somatic BAP1 mutation is infrequent in epithelial cancers." (PMID 36669126, 2023). "A recent study showed that BAP1 is rarely mutated in breast cancers and promotes breast cancer cell proliferation and metastasis." (PMID 36754982, 2023). "BAP1 direct physical interaction with BRCA1-RING finger domain was associated to enhancement of BRCA1 tumour suppressor activity in breast cancer." (PMID 36318367, 2022). "BAP1 germline variants are rare in patients with breast cancer undergoing genetic testing for hereditary cancer." (PMID 35381901, 2022). "We present a case of a patient with BAP1 cancer syndrome who developed early-onset, BAP1-deficient breast cancer and had a complete and ongoing response to monotherapy with a PD-L1 inhibitor." (PMID 35381901, 2022). "At the moment, breast cancer screening is offered to BAP1 carriers on the basis of personal risk factors and family history." (PMID 35381901, 2022). "A study involving 760 unselected Australian breast cancer patients detected loss of immunohistochemical BAP1 expression indicating biallelic inactivation in three patients (0.4%)." (PMID 35381901, 2022). "Her half-sister, who was also a carrier of the familial BAP1 variant developed early-onset breast cancer as well." (PMID 35381901, 2022). "A significant role in the regulation of breast cancer centrosomes is also played by deubiquitylase BAP1 (BRCA1-associated protein-1)." (PMID 34830792, 2021). "LncFOXO1 is a novel lncRNA, which has been recently reported to inhibit the growth of breast cancer cells by regulating BRCA1-associated protein 1 (BAP1)." (PMID 31217928, 2019). "Although loss of BAP1 function is seen at far lower rates in breast carcinoma (1%) and non-small cell lung carcinoma (1%), the high incidence of these cancers translates to a large cohort of patients." (PMID 29345617, 2018). "BRCA1-associated protein 1 (BAP1) was originally identified as a protein that interacted with the RING finger domain of the breast cancer susceptibility gene product BRCA1." (PMID 26885612, 2016). "Among the candidate genes, BAP1 (BRCA1-associated protein 1) drew our special attention because it has been reported to localize in the nucleus and promote breast cancer cell growth similar to KLF5 (refs 31, 32, 33)." (PMID 26419610, 2015). "Breast cancer, occasionally with early onset has been described in several families, most notably in the study by Popova and colleagues, which was the first to report the association of BAP1 germline pathogenic variants with RCC." (PMID 35381901, 2022). "Even if the risk of developing breast cancer is low or moderate for most patients, screening might be advisable if BAP1-deficient breast cancers are confirmed to be associated with poor prognosis and/or warrant specific therapeutic approaches." (PMID 35381901, 2022). "We present a case of BAP1-deficient breast cancer arising in a patient with BAP1 cancer syndrome." (PMID 35381901, 2022). "Our report implies there is an association between BAP1 cancer syndrome and breast cancer." (PMID 35381901, 2022). "We hypothesize that the tumor’s immunophenotype and the patient’s complete and durable response to ICI might be the result of BAP1-deficiency, making BAP1 alterations a putative biomarker for response to immunotherapy in breast cancers that harbor them." (PMID 35381901, 2022).
breast carcinoma (continued). "A previous report suggested that BAP1 prevents chromosome instability in breast cancer cells, indicating that BAP1 mutations could lead to the occurrence of other de novo mutations in PDX tumors." (PMID 33107222, 2021). "For example, BAP1 loss or germline mutations have been linked to prolonged survival in malignant pleural mesothelioma, and BAP1 overexpression appears to promote basal type breast cancers and myeloid neoplasms harboring certain ATRX mutations." (PMID 31903168, 2019). "However, according to cBioPortal.org, there is a low frequency of BAP1 somatic mutation (1.8%) in breast cancer." (PMID 30716094, 2019). "A recent study has linked the deubiquitination of γ-tubulin by BAP1 to breast cancer." (PMID 25605410, 2015). "Therefore, the identification of the loss of BAP-1 expression in some tumors, such as ovarian, lung, and breast carcinomas, has suggested that BAP-1 could be considered a tumor suppressor gene." (PMID 36553016, 2022). "For instance BAP1 deubiquitination modified the transcription factor KLF5 in breast cancer cells promotes the growth of tumor cells, and the proliferation and invasion of tumor cells are weakened after BAP1 knocking down." (PMID 40918144, 2025). "BAP1 was first identified and isolated from breast cancer and lung cancer cell lines in 1998, named for its binding to the RING domain of the BRCA1 protein." (PMID 40918144, 2025). "BAP1 was increased by the E2 treatment, which has an important effect on the breast cancer growth, and cell growth was decreased by BAP1 C91A overexpression." (PMID 38708315, 2024). "Three DUBs, including ATXN3L, BAP1, and USP3 can deubiquitinate and stabilize KLF5 that are implicated in the pathological development of breast cancer." (PMID 38468288, 2024). "For instance, BAP1’s role in the deubiquitination of KLF5 encourages the progression of breast carcinoma." (PMID 37573347, 2023). "For example, BAP1 expression can promote pro-oncogenic pathways, including breast cancer cell proliferation and radioresistance in head and neck cancer." (PMID 36669126, 2023). "Other alleged tumours in BAP1-TPDS comprise: breast cancer, neuroendocrine carcinoma, non-small-cell lung adenocarcinoma, thyroid cancer and urinary bladder cancer." (PMID 38087265, 2023). "In breast cancer cell lines, BAP1 plays an oncogenic function by directly deubiquitinating and stabilizing KLF5 (Kruppel-like factor 5)." (PMID 36318367, 2022). "BRCA1-associated protein 1 (BAP1) stabilizes KLF5 by removing the ubiquitin chain, thereby promoting the occurrence and metastasis of breast cancer." (PMID 36613989, 2022). "This case strengthens the evidence for including breast cancer in the BAP1 cancer syndrome tumor spectrum with implications for future cancer prevention programs." (PMID 35381901, 2022). "The BAP1-positive proband in one of their families developed bilateral early onset breast cancer, in addition to several RCCs." (PMID 35381901, 2022). "For instance, BAP1 has been demonstrated to stabilize an oncogenic transcription factor KLK5 in breast cancer, promoting breast cancer progression and metastasis." (PMID 35194152, 2022). "There is some evidence for including breast cancer in the BAP1 cancer syndrome tumor spectrum, but its high prevalence in the general population is a confounder increasing the likelihood of chance association." (PMID 35381901, 2022). "Emerging studies from other groups as well as our own have revealed a critical oncogenic role of BAP1 in multiple human cancers, including breast cancer, leukemia, and small cell lung cancer (SCLC)." (PMID 36180891, 2022). "The analysis of transcriptome profiling data sets indicates that lower BAP1 expression imparts an unfavorable prognosis for breast cancer patients." (PMID 35381901, 2022). "In KLF5-positive breast cancer cells, BAP1 reduced p27 expression and promoted cell proliferation in vitro." (PMID 35884607, 2022).
breast carcinoma (continued). "It has been shown that BAP1 promotes the development of breast cancer by releasing the ubiquitin modification of the transcription factor human Krüppel‐like factor 5 (KLF5)." (PMID 33529461, 2021). "In human breast cancer, BAP1 functions as deubiquitinase to stabilize the transcription factor KLF5—which is highly expressed in basal-like breast cancer—and promotes breast cancer cell proliferation, migration, and tumor growth." (PMID 33483476, 2021). "It has been shown previously that loss of BAP1 expression can be utilized as a prognostic marker in RCC and breast cancer." (PMID 34201614, 2021). "Several different miRNAs were shown to influence BAP1 function in cervical cancer, renal carcinoma, lung cancer, breast cancer, and others." (PMID 32131485, 2020). "Depletion of BAP1 in breast cancer cell linescaused growth inhibition that was dependent on its deubiquitinating activity (Machidaet al., 2009)." (PMID 32422649, 2020). "Herein, we analyzed publicly available data sets from the TCGA and showed that BAP1 plays a prognostic role in both UM and breast cancer." (PMID 30716094, 2019). "BAP1 also regulates mitotic spindle organization and prevents genomic instability by deubiquitinating γ-tubulin in breast cancer cells." (PMID 30669483, 2019). "For example, target genes of BAP1 deubiquitination include mutant ATRX in myeloid neoplasms and Krüppel-like factor 5 (KLF5) in basal-like breast cancers, which both become stabilized by BAP1 and consequently accelerate tumor growth." (PMID 31903168, 2019). "In summary, our findings suggest that BAP1 expression has prognostic significance in both UM and breast cancer." (PMID 30716094, 2019). "Of note, all highly positively correlated genes with BAP1 in UM and breast cancer are located in chromosome 3." (PMID 30716094, 2019). "Note that IP6K1 was not in the list of highly correlated genes in the all four categories of breast cancer, because its correlation coefficient with BAP1 in the black-alive category was 0.73, which was less than the threshold 0.8." (PMID 30716094, 2019). "We discovered that there are three genes (DHX30, USP19, and RBM15B), which are highly positively correlated with BAP1 in both black and white breast cancer patients." (PMID 30716094, 2019). "BAP1 is located in the 3p21 chromosomal region, which is commonly deleted in breast cancer patients." (PMID 30716094, 2019). "Gene copy number variation (CNV) analysis of SETD2, BAP1, PARP-3 and PBRM1 within a panel of nine breast cancer cell lines demonstrated single copy number loss of all candidate genes within five (56%) cell lines (including 21NT cells)." (PMID 28977912, 2017). "Taken together, these results demonstrate that BAP1 promotes HCC1806 breast cancer tumorigenesis partially by stabilizing KLF5." (PMID 26419610, 2015). "Research into BAP1 has gained attention due to its role in lung and breast cancers and tumor suppression." (PMID 25605410, 2015). "BAP1 promotes breast cancer cell proliferation and migration in vitro and tumour growth and lung metastasis in vivo." (PMID 26419610, 2015). "In this study, we discovered a novel positive regulatory mechanism for KLF5 and the functional mechanism by which BAP1 promotes breast cancer growth and metastasis." (PMID 26419610, 2015). "Besides UCHL1, some other DUBs, such as ATXN3L, BAP1, and USP3 can deubiquitinate KLF5 and are implicated in the pathological development of breast cancer." (PMID 38468288, 2024). "Furthermore, we identified additional breast cancer genes deleted more frequently in warm/hot tumors than in cold tumors (BAP1, PBRM1, NOTCH1, CCND1, RB1)." (PMID 38714665, 2024). "While these findings suggest that BAP1 functions as a tumor suppressor, recent data also suggest that BAP1 might play tumor-promoting roles in certain cancers, such as breast cancer and hematopoietic malignancies." (PMID 36754982, 2023).
breast carcinoma (continued). "Moreover, BAP1 is a DUB for the transcription factor KLF5 and depletion of BAP1 inhibits breast cancer cell proliferation and tumor growth in vitro and in vivo in an KLF5-dependent manner." (PMID 37543638, 2023). "Notably, several breast cancer cell, colon cancer cell and lung cancer cell lines presented robust nPD-L1 signals, which were free of classic mutations (e.g., GNA11/GNAQ/BAP1) in UM." (PMID 36977660, 2023). "BAP1 is well-known for its role in breast cancer development." (PMID 35884607, 2022). "As a result, depletion of BAP1 inhibits breast cancer tumorigenicity and lung metastasis." (PMID 35194152, 2022). "When testing for somatic variants, BAP1 inactivation was seen in less than 1% of breast cancer cases, suggesting it is not a major breast cancer gene." (PMID 35381901, 2022). "In human breast cancer, the oncogenic transcription factor KLF5 (highly expressed in basal-like breast cancer) could be stabilized by BAP1, which further promotes breast cancer cell development both in vitro and in vivo." (PMID 35194152, 2022). "Overexpression of BAP1 in breast cancer MCF-7 cells inhibits the formation of soft agar clones." (PMID 36003792, 2022). "However, the overall incidence of breast cancer in their BAP1-positive families was deemed insufficient to include it in the BAP1 cancer syndrome spectrum." (PMID 35381901, 2022). "Additionally, CERS6-AS1 functioned as a ceRNA to regulate miR-125a-5p, upregulate BAP1 expression and promote breast cancer cell growth." (PMID 34168120, 2021). "Interaction of BAP1 with BRCA1 has been shown to inhibit breast cancer growth." (PMID 33916178, 2021). "The overexpression of BAP1 in the breast cancer MCF‐7 cell line inhibits cell colony formation." (PMID 33529461, 2021). "A previous study on the expression of BAP1 tumor suppressor gene in 1222 patients with TCGA breast cancer data reported that the expression of BAP1, which enhances BRCA1-mediated suppression of cell proliferation through BRCA1 stabilization, is highly correlated with USP19 expression." (PMID 34439131, 2021). "However, the dead UM and breast cancer patients had lower levels of BAP1 expression compared with surviving patients." (PMID 30716094, 2019). "This suggests that haploinsufficiency of BAP1, likely as part of the 3p21 chromosomal deletion, could be still important in the pathogenesis of breast cancers." (PMID 30716094, 2019). "Our data show that BAP1 expression is decreased in a subset of UM and breast cancer patients." (PMID 30716094, 2019). "However, its correlation coefficient with BAP1 in the other three categories of breast cancer patients was greater than 0.8." (PMID 30716094, 2019). "Importantly, in breast cancer patients, the lowest BAP1 expression levels corresponded to the dead young patients (age at diagnosis < 46)." (PMID 30716094, 2019). "Due to the high frequency of gene copy number loss within breast cancer cells, our results provide additional evidence that SETD2, BAP1, PBRM1 and PARP-3 may function as tumour suppressors in breast cancer cells." (PMID 28977912, 2017). "Therefore, it is urgent to validate the function of BAP1 in breast cancer in vivo and characterize its functional mechanisms." (PMID 26419610, 2015). "Since high KLF5 mRNA and protein levels have been reported as a potent biomarker for unfavourable prognosis for breast cancer patients, we tried to test whether BAP1 can also serve as a biomarker for prognosis for breast cancer patients." (PMID 26419610, 2015). "Our findings imply that BAP1 could serve as a potential therapeutic target in basal-like breast cancer." (PMID 26419610, 2015). "In addition, MiR-125a-5p functions as a tumour suppressor in breast cancer by downregulating BAP1." (PMID 38914670, 2024). "In addition, miR-125a-5p acts as a tumor suppressor for breast cancer by down-regulating BAP1." (PMID 38914670, 2024).
breast carcinoma (continued). "Moreover, we found a uniform reduced BAP1 protein levels in renal carcinoma cell lines, lung cancer cell lines, and breast cancer cell lines in comparison with the normal renal cells (HK‐2 cells), lung cells (WI38 and 16HBE cells), and breast cells (MCF10A cells), respectively." (PMID 33155366, 2021). "This suggests that BAP1 could be an important driver for tumorigenesis in breast cancer." (PMID 30716094, 2019). "Also, a recent study shows that biallelic inactivation of BAP1 is rare in breast cancer." (PMID 30716094, 2019). "Similar results were found in BAP1-deficient cholangiocarcinoma TFK-1 cells, UM UPMM2 cells, breast cancer HCC-1187 cells, and ccRCC 786–0 cells with wild-type BAP1 knocked out using two different CRISPR-Cas9 guided-RNAs." (PMID 40754831, 2025). "Next, to verify the relationship between Med1 and BAP1 protein expression, it was treated with EGF, E2, and TGF-β, which are known to play an important role in breast cancer growth regulation." (PMID 38708315, 2024). "A recent study showed that BAP1 forms a complex with the transcription factor KLF5 to stimulate cell cycle progression and promotes breast cancer cell proliferation by deubiquitinating and stabilizing KLF531." (PMID 36754982, 2023). "Transcription factor KLF transcription factor 5 (KLF5) is a member of the BAP1/HCF-1 complex, which is expressed in breast cancer tissues and promotes cancer cell proliferation and metastasis." (PMID 36613989, 2022). "BAP1 interacted with KLF5 and led to its stability and exerted its oncogenic function in breast cancer." (PMID 34226507, 2021). "Pedigrees for the cases identified with BAP1 germline VUS show strong family history of cancers from the paternal side and early onset cancers, including renal and breast cancers." (PMID 33240524, 2020). "BRCA1-associated protein-1 (BAP1) is found to be expressed at a low level in breast cancer patients, while RBM15B has a positive correlation with BAP1 in invasive breast cancer." (PMID 33362863, 2020). "DHX30 has the highest positive correlation with BAP1 in black-alive and white-dead categories, while USP19 has the maximum positive correlation with BAP1 in black-dead and white-alive breast cancer categories." (PMID 30716094, 2019). "We next performed real-time qPCR on the breast cancer cell lines and normal breast tissues using primer sequences specific to the candidate genes SETD2, BAP1 PBRM1 and PARP-3 (Figure 2Ci-2Civ)." (PMID 28977912, 2017). "Here, the authors show that the debuquitinase BAP1 directly stabilizes KLF5, thus promoting basal-like breast cancer cell-cycle progression and metastasis." (PMID 26419610, 2015). "Collectively, our findings not only identify BAP1 as the DUB for KLF5, but also reveal a critical mechanism that regulates KLF5 expression in breast cancer." (PMID 26419610, 2015). "To explore the roles of BAP1 and KLF5 in breast cancer metastasis, we examined breast cancer cell migration and invasion." (PMID 26419610, 2015). "Moreover, BAP1 was found to stabilize the transcription factor KLF5 and subsequently promoted the breast cancer cell proliferation and tumor growth in vitro and in vivo." (PMID 37543638, 2023). "A single case of a BAP1-defficient breast cancer responding to atezolizumab is by no means evidence of a role for BAP1 inactivation in response to immunotherapy, but we believe our findings are interesting and warrant further investigation." (PMID 35381901, 2022). "The deubiquitinase (DUB) BAP1 had been reported to regulate KLF5 stability in breast cancer cells, so we hypothesize that LINC00152 mediates KLF5 depending on the binding of BAP1 and KLF5." (PMID 33842324, 2021). "In addition, BAP1 as a deubiquitinase enhanced cell proliferation and metastasis via deubiquitinating KLF5 in breast cancer cells." (PMID 34226507, 2021).